GPR17 (G protein-coupled receptor 17)
Description:
Dual specificity receptor for uracil nucleotides and cysteinyl leukotrienes (CysLTs). Signals through G(i) and inhibition of adenylyl cyclase. May mediate brain damage by nucleotides and CysLTs following ischemia.
Tractability: Small molecule: a high-quality ligand is known; it belongs to a druggable protein family. Antibody: its Gene Ontology location is reachable by antibodies, with high confidence; UniProt places it where antibodies can reach, with medium confidence; UniProt predicts a signal peptide or a membrane-spanning region. PROTAC: a small molecule that binds it is known.
Target class: Leukotriene receptor; Small molecule receptor (family A GPCR); Membrane receptor; Lipid-like ligand receptor (family A GPCR); Family A G protein-coupled receptor
Gene: Protein-coding gene on chromosome 2 (127,645,864 to 127,656,181, forward strand). Ensembl gene ENSG00000144230.
Subcellular location: Cell membrane
Subcellular location (Human Protein Atlas): Vesicles
Pathways (Reactome):
Signal Transduction: G alpha (i) signalling events; G alpha (q) signalling events; Leukotriene receptors; P2Y receptors
Gene Ontology:
Molecular function: chemokine receptor activity; G protein-coupled receptor activity; receptor serine/threonine kinase binding
Biological process: G protein-coupled receptor signaling pathway; chemokine-mediated signaling pathway; oligodendrocyte differentiation
Cellular component: plasma membrane; membrane
Genetic constraint (gnomAD): Loss-of-function variants: 4 observed, 3.33 expected, observed/expected ratio (o/e) 1.2, 90% interval 0.55 to 1.89. That is too few expected variants to judge how well the gene tolerates losing a copy. Missense variants: 463 observed, 472.87 expected, observed/expected ratio (o/e) 0.98, 90% interval 0.91 to 1.06. Synonymous variants: 209 observed, 212.43 expected, observed/expected ratio (o/e) 0.98, 90% interval 0.88 to 1.1.
Homologues: Orthologues: chimpanzee GPR17 (99% identical), macaque GPR17 (97% identical), dog GPR17 (91% identical), rabbit GPR17 (91% identical), mouse Gpr17 (90% identical), rat Gpr17 (90% identical), pig GPR17 (89% identical), guinea pig GPR17 (87% identical), zebrafish gpr17 (55% identical), tropical clawed frog gpr17 (50% identical). Paralogues in human: P2RY10 (31% identical), CYSLTR2 (30% identical), F2R (29% identical), LPAR6 (29% identical), GPR18 (28% identical), GPR4 (28% identical), LPAR4 (28% identical), CYSLTR1 (27% identical), F2RL1 (27% identical), GPR20 (27% identical), F2RL2 (25% identical), F2RL3 (25% identical), and 4 more.
Diseases named in the same sentence as GPR17 in open-access papers:
GPR17 is named in the same sentence as 52 diseases in open-access papers, as found by Europe PMC text mining. Sharing a sentence is not in itself a finding about the gene and the disease. The quoted sentences say what the papers report.
glioma (13 papers, 2016 to 2026). A benign or malignant brain and spinal cord tumor that arises from glial cells (astrocytes, oligodendrocytes, ependymal cells). "Further, in TCGA database, we found that glioma patients with IDH mutations showed higher expression level of GPR17 than the patients with wild-type IDH." (PMID 34120140, 2021). "Until now, although several studies have mentioned that GPR17 was involved in glioma, the functions of GPR17 during glioma development and the underlying mechanism were largely unstudied." (PMID 34120140, 2021). "To date, GPR17 has been implicated to play roles in glioma development." (PMID 34120140, 2021). "Over-expression of GPR17 in the glioma cell lines U87MG and U251 induced apoptosis by increasing ROS levels." (PMID 37990234, 2023). "A previous study has demonstrated that G-protein-coupled receptor GPR17 inhibits glioma development by increasing polycomb repressive complex 1-mediated ROS production." (PMID 38003496, 2023). "In an alternate study, the activation of KLF9 by G protein-coupled receptor 17 (GPR17) suppressed glioma development." (PMID 36077352, 2022). "The inhibitory effects of GPR17 on glioma cell viability make it a potential therapeutic target for glioma." (PMID 34120140, 2021). "In this study, we found that GPR17 was a potential therapeutic target against glioma, as either overexpression or pharmacological activation of GPR17 effectively inhibited glioma tumorigenesis." (PMID 34120140, 2021). "Intriguingly, in vitro analysis revealed that activation of the GPR17 agonist favored the selective survival of Oligo 2 cells and altered the proliferative ability of glioma cells by decreasing the number of neurospheres." (PMID 34359676, 2021). "On the other hand, both RNF2 and H2AK119ub recruitments were reduced upon GPR17 overexpression or activation by MDL29951 treatment in glioma cells." (PMID 34120140, 2021). "To directly test the potential role of GPR17 in glioma development, we generated a stable GPR17-overexpressing cell line with a common used glioma cell line, U87MG (U87-GPR17)." (PMID 34120140, 2021). "In our study, using multiple approaches, we revealed the inhibitory role of GPR17 in glioma development, and demonstrated the pathway and the key molecules that mediated its biological effects in glioma cells." (PMID 34120140, 2021). "Using GPR17 agonist to activate GPR17 activity, we discovered that GPR17 had a therapeutic potential in glioma treatment." (PMID 34120140, 2021). "Data mining with human LGG and GBM samples reveals that GPR17 is negatively correlated with glioma development." (PMID 34120140, 2021). "We therefore examined the ROS levels in our GPR17-overexpressing and silencing glioma cells, aiming to reveal the molecular basis leading to the suppressed cell proliferation and survival by GPR17." (PMID 34120140, 2021). "In this study, we found that GPR17 increased ROS level in glioma cells through a regulation on SOD1 gene expression." (PMID 34120140, 2021). "To demonstrate the molecular basis of GPR17 in glioma development, we stably overexpressed or knocked down GPR17 in two glioma cell lines, U87MG (U87) and U251." (PMID 34120140, 2021). "Overexpressing GPR17 inhibits glioma cell proliferation and induces apoptosis by raising ROS levels." (PMID 34120140, 2021). "Our findings have thus identified GPR17 as a key regulator of glioma development and a potential therapeutic target for gliomas." (PMID 34120140, 2021). "Another study reported that within the NF-κB-RNF2-KLF9 cascade, KLF9 serves as a key downstream effector mediating GPR17’s antiproliferative and pro-apoptotic roles in glioma pathogenesis, offering a dual targeting strategy involving GPR17 activation or KLF9 modulation." (PMID 40860800, 2025). "Moreover, NEU4 and GPR17 expression was enriched in the tumor cell clusters of both sporadic and NF1-associated low-grade gliomas (pilocytic astrocytoma)." (PMID 41497446, 2025).
glioma (continued). "HBS-101, a novel midkine inhibitor, reduced optic nerve proliferation, normalized RNFL thickness, and decreased the expression of tumor (Neu4, Gpr17) and TME (Ccl2, Ccl3, Ccl4, Ccl5) genes, supporting its continued development as a targeted therapy for pediatric NF1-associated glioma." (PMID 41497446, 2025). "SOX10 and GPR17 were primarily expressed in glioma cells from the low-edema group of patients." (PMID 39534094, 2024). "GPR17 expression is also higher in low-grade gliomas than in healthy brain tissue." (PMID 36765904, 2023). "Here, we identify GPR17 as a potential target to treat glioma." (PMID 34120140, 2021). "In addition, computational data analysis on the RNA-seq also have reported on the expression of GPR17 in 511 low-grade glioma (LGG) and 156 glioblastoma samples." (PMID 34440745, 2021). "Notably, so far, several GPR17 agonists or antagonists have been established, which will greatly facilitate the application of targeting GPR17 for glioma therapy." (PMID 34120140, 2021). "Immunofluorescent imaging against BrdU indicated that GPR17 inhibited glioma cell proliferation." (PMID 34120140, 2021). "As some glioma originated from oligodendrocyte lineage cells, we speculated that GPR17 played a role in glioma development." (PMID 34120140, 2021). "GPR17-overexpressing glioma cells are less tumorigenic in the brain than in control cells." (PMID 34120140, 2021). "To test the possibility, we used MDL29951, a GPR17 agonist, to investigate whether activation of GPR17 showed inhibitory effects on glioma development." (PMID 34120140, 2021). "Although GRP17 was found to be expressed in glioma, whether and how GPR17 was involved in the glioma development remain largely unknown." (PMID 34120140, 2021). "Therefore, we paid our efforts to study the role of GPR17 during glioma development, and sought to evaluate its therapeutic potential for glioma." (PMID 34120140, 2021). "An increase in GPR17 expression can cause the proliferation and migration of GBM cells, particularly with an increase in the expression of this receptor by long non-coding RNA (lncRNA) colorectal neoplasia differentially expressed (CRNDE) in low-grade glioma cells." (PMID 36765904, 2023). "Furthermore, activation of GPR17 by its agonist inhibits glioma formation." (PMID 34120140, 2021). "In glioma cells, KLF9 was identified to suppress the expression of SOD1, accomplishing the regulatory effects of GPR17 on ROS level." (PMID 34120140, 2021). "As the role of KLF9 in oxidative stress has been widely reported, we therefore chose KLF9 as a downstream target for GPR17 and RNF2 to control ROS level in glioma cells." (PMID 34120140, 2021). "Taken together, our results indicated that GPR17 regulated RNF2 expression through a cAMP–PKA–p65 regulatory axis, and RNF2 mediated the functions of GPR17 in glioma cells." (PMID 34120140, 2021). "The augmented ROS level was the key signature for the effect of GPR17 on glioma cell death, as the elimination of excessive ROS by NAC abolished the effects of GPR17." (PMID 34120140, 2021). "Purinergic signaling related genes such as GPR17, VEGFA and CCL2 are involved in inflammation leading to glioma growth." (PMID 27323413, 2016). "KLF9 mediates the functions of GPR17 and RNF2 in glioma cells." (PMID 34120140, 2021). "Besides, the protein levels of p-PKA and RNF2 were both significantly decreased in U87 xenografts after MDL29951 treatment, which further revealed the role of GPR17 activation in the control of PKA signaling activity and RNF2 expression in glioma." (PMID 34120140, 2021). "When the GPR17-silencing cells were treated with PRT4165, the ROS levels or the viable cell numbers returned to similar levels as those in U87/U251-shScr cells, suggesting that the inhibitory effect of GPR17 on glioma development was mediated by PRC1-mediated histone monoubiquitination." (PMID 34120140, 2021).
glioma (continued). "Therefore, we hypothesized that KLF9 might mediate the regulatory effects of GPR17 and RNF2 on ROS levels and glioma tumorigenesis." (PMID 34120140, 2021).
Stroke (9 papers, 2008 to 2025). Sudden impairment of blood flow to a part of the brain due to occlusion or rupture of an artery to the brain. "In various in vivo neurodegenerative models characterized by myelin loss (stroke, trauma, demyelination, and experimental autoimmune encephalomyelitis), Gpr17 was abnormally up-regulated in OPCs around lesion sites." (PMID 29540737, 2018). "Besides EAE (the present study), several other distinct models of brain disease, including stroke, trauma, Alzheimer's have been associated to persistent GPR17 upregulation and impaired progression along the oligodendrocyte lineage, eventually resulting in dysfunctional repair." (PMID 29424466, 2018). "On the contrary, at later stages after stroke, microglia lose their pro‐remyelinating functions in favour of an inflammatory and dystrophic state that hinders GPR17‐expressing OPC maturation." (PMID 39703181, 2025). "GPR17, a receptor transiently expressed on early OPCs, has emerged as a target to implement stroke repair through stimulation of OPC maturation." (PMID 28594400, 2017). "In a rat brain focal ischemia model, the selective in vivo knock down of GPR17 by anti-sense technology or P2Y/CysLT antagonists reduced progression of ischemic damage, thus highlighting GPR17 as a novel therapeutic target for stroke." (PMID 18533035, 2008). "Considering recent studies pointing towards sexual dimorphism in glial cell responses after stroke, we further investigated the possible relationships between GPR17+, AIF1+, and GFAP+ cells within the PI area of chronic lesions by performing sex‐specific correlation analyses on our cases." (PMID 39703181, 2025). "Infusion of pro-regenerative microglial EVs in the ipsilateral corpus callosum of ischemic mice starting from day 14 post-MCAO, corresponding to the late stage after stroke, specifically increased the number of GPR17-expressing OPCs at lesion boundaries and enhanced their maturation." (PMID 36176630, 2022). "It has been reported that GPR17 mediates immune response and ischemic/inflammatory states, including stroke and some neurodegenerative diseases GPR17 receptor may be a target for stroke, brain and spinal cord injury, and diseases characterized by neuronal and myelin dysfunctions." (PMID 34483854, 2021). "By using a model of experimental stroke induced by MCAO, we also analyzed the effects induced by microglial EVs on GPR17-expressing OPCs, a cluster of oligodendrocytes particularly reactive to brain damage." (PMID 36176630, 2022). "It has been demonstrated that in animal models of stroke treatment with Cangrelor, and also with MTK and blockade of GPR17 with antisense technology, led to decreased infarct volumes." (PMID 34769111, 2021). "To solve this problem, in this study we induced stroke by permanent middle cerebral artery occlusion (MCAo) in GPR17iCreERT2:CAG-eGreen florescent protein (GFP) transgenic mice, the first fluorescent reporter mouse line for GPR17 fate-mapping studies." (PMID 28594400, 2017).
multiple sclerosis (8 papers, 2008 to 2025). A progressive autoimmune disorder affecting the central nervous system resulting in demyelination. "Among these, G protein-coupled receptor 17 (GPR17) has emerged as a promising remyelinating target in multiple sclerosis (MS)." (PMID 35954217, 2022). "Specifically, we suggest GPR17 as a novel target for therapeutic manipulation to foster repair of demyelinating wounds, the types of lesions that also occur in patients with multiple sclerosis." (PMID 18974869, 2008). "In initial studies, the mRNA for GPR17 was also found to be increased in the spinal cord of mice with experimental autoimmune encephalomyelitis (EAE) and in the spinal lesions of multiple sclerosis patients." (PMID 29424466, 2018).
brain ischemia (6 papers, 2008 to 2023). Diminished or absent blood supply to the brain caused by obstruction (thrombosis or embolism) of an artery resulting in neurologic damage. "In support of this, GPR17 positive cells are upregulated in response to cerebral ischemia and associated with oligodendrocyte differentiation." (PMID 24498301, 2014). "GPR17 mediates microglial inflammation in the chronic phase of cerebral ischemia and regulates allergic pulmonary inflammation." (PMID 37990234, 2023). "Studies have reported increased expression of GPR17 in patients with traumatic brain injury, cerebral ischemia, and other animal models of central nervous system damage." (PMID 37990234, 2023). "Based on this and on the demonstration that both cysteinyl-LTs and nucleotides massively accumulate in ischemic brain we also analyzed the role of GPR17 in a model of focal brain ischemia in the rat." (PMID 18533035, 2008). "This indicates GPR17 as a possible target for pharmacological intervention in neurodegeneration processes including cerebral ischemia and demyelinating diseases." (PMID 18974869, 2008). "However, being GPR17 completely downregulated in myelin-producing oligodendrocytes, its actual role in determining the final fate of OPCs after cerebral ischemia is still uncertain." (PMID 28594400, 2017). "Interestingly, pathologically increased levels of GPR17 have been found in several animal models of disease, including focal demyelination, brain ischemia, amyotrophic lateral sclerosis, and traumatic brain injury, suggesting that aberrant GPR17 upregulation may contribute to remyelination failure." (PMID 33925469, 2021). "GPR17 has been shown to be expressed by a subset of OPCs and it is thought that these cells may operate as an early sensor of brain damage whereby they are activated by uracil nucleotides and cysteinyl leukotrienes which are increased in response to cerebral ischemia." (PMID 24498301, 2014). "Thus, GPR17 is the first fully characterized "hybrid" GPCR responding to two unrelated families of non-peptide signalling molecules and represents a previously unexplored therapeutic target for brain ischemia." (PMID 18533035, 2008).
glioblastoma (6 papers, 2021 to 2025). The most malignant astrocytic tumor (WHO grade IV). "Similarly, GPR17 is linked to an altered pathway in glioblastoma and its targeting has led to a significant reduction in neurospheres in rodent models." (PMID 34298641, 2021). "Previously, GPR17 was characterized as a prognostic signature for glioblastoma patients with wild-type IDH." (PMID 34120140, 2021). "The discovery ofa potential ligand-targeting G protein-coupledreceptor 17 (GPR17) is important for developing chemotherapeutic agentsagainst glioblastoma multiforme (GBM)." (PMID 34304559, 2021). "GPR17 expression is associated with higher survival for both low-grade glioma (LGG) and glioblastoma (GBM)." (PMID 34359676, 2021).